INS (insulin)
Diseases named in the same sentence as INS in open-access papers (continued):
Sharing a sentence is not in itself a finding about the gene and the disease.
Insulin resistance (continued). "Rapid pubertal growth and puberty-related insulin resistance increase the insulin demand and cause thereby ER stress in the beta cells rendering them vulnerable." (PMID 37079135, 2023). "In the recent years, the InsuTAG index has garnered much interest as it combines insulin and triglycerides as biochemical parameters to evaluate for risk of insulin resistance in an individual." (PMID 37945732, 2023). "Another study has shown that muscle loss induces insulin resistance by reducing the mass of insulin response target tissues, which promotes metabolic syndrome and obesity." (PMID 37402414, 2023). "The classical dogma of glucocorticoid-induced insulin resistance is that it is caused by the transcriptional activation of hepatic gluconeogenic and insulin resistance genes by the glucocorticoid receptor (GR)." (PMID 37253782, 2023). "The SOCS3 protein is the main inhibitor of leptin and insulin signaling which causes cellular leptin and insulin resistance and dampens energy production." (PMID 37207231, 2023). "Insulin resistance (IR) is a pathophysiological hallmark of type 2 diabetes with reduced insulin sensitivity being detectable up to 5 years prior to the diagnosis of type 2 diabetes." (PMID 37716952, 2023). "T2DM presents with a spectrum of dysfunctions, characterized by hyperglycemia, insulin resistance and consequent pancreatic β-cell failure, and reduced insulin output, causing a series of complications if left untreated." (PMID 37032867, 2023). "Both ECMR and EnNaC activation lead to reduced endothelial NO synthase (eNOS) activation and NO bioavailability in association with reduced insulin-mediated capillary recruitment, glucose uptake, and systemic and tissue insulin resistance." (PMID 37610001, 2023). "Overall, insulin resistance is proposed to be associated with the development of salt-sensitive hypertension through the anti-natriuretic effect of insulin." (PMID 36901725, 2023). "Increased insulin resistance (IR) and decreased insulin secretion comprise the main pathogenic mechanisms underlying T2DM development." (PMID 38066741, 2023). "IL-6 causes a low-grade inflammation that affects insulin signaling and triggers insulin resistance." (PMID 37009872, 2023). "T2D is primarily caused by the development of insulin resistance, a dysfunctional metabolic state in which the peripheral tissues (i.e., skeletal muscle, adipose and liver) are unable to effectively respond to insulin and utilize glucose from the blood." (PMID 37759961, 2023). "The associated increase in insulin levels and in insulin resistance with obesity was reported during the first trimester of pregnancy; observations comparable to other studies, emphasizing the risk of hyperinsulinemia among obese women." (PMID 36520252, 2023). "Type 2 diabetes mellitus (T2DM) is a non-infectious metabolic disease characterized by elevated blood glucose levels caused by impaired insulin secretion, insulin resistance, or both." (PMID 38260058, 2023). "T2DM has been reported to have a higher insulin level in serum and is characterized by insulin resistance, which is caused by the high-fat diet in STZ-induced diabetic rats." (PMID 37569125, 2023). "In summary, SLCO1B1 rs4149056-C did not have a significant association with the risk of T2D, elevated glucose concentration, insulin resistance, or impaired insulin secretion." (PMID 37795366, 2023). "Peripheral Ang 1–7 has been associated with increases in glucose uptake in insulin‐target tissues and insulin resistance prevention." (PMID 36905124, 2023). "These modifications have the potential to negatively impact the insulin sensitivity of skeletal muscles and increase the risk of insulin resistance and type-2 diabetes during skeletal muscle aging." (PMID 36987444, 2023).
Insulin resistance (continued). "It has been demonstrated that insulin-stimulated muscle glucose uptake is highly susceptible to insulin resistance attributed to impaired GLUT4 translocation, and stimulating GLUT4 translocation is helpful to maintain glucose homeostasis." (PMID 36677541, 2023). "In β cells, aSyn has been implicated in the regulation of basal insulin secretion, and low levels of circulating aSyn are linked to peripheral insulin resistance." (PMID 36793785, 2023). "LCACs are associated with insulin resistance because chronic overnutrition can lead to lipotoxicity and interference with insulin signaling via multiple mechanisms, including incomplete β oxidation at the mitochondrial membrane." (PMID 37552540, 2023). "SCFAs and genera whose relative abundance was higher in the VK6 group were associated with reductions in serum Hb1Ac, glucose, insulin and insulin resistance." (PMID 37147641, 2023). "The concentrations of glycine and serine are positively associated with insulin sensitivity and secretion whereas inversely correlated with insulin resistance." (PMID 37875989, 2023). "The underlying pathophysiologies of GDM and T2DM are increased insulin resistance and defects in insulin secretion." (PMID 37107681, 2023). "In NAFLD, sarcopenia is closely associated with insulin resistance and results from the atrophy of skeletal muscle, an insulin target organ." (PMID 36839249, 2023). "ZWFL was associated with 0.19 (95% CI 0.07, 0.31) higher serum insulin concentration (in logarithm transform, pmol/L) in boys, suggesting higher insulin resistance with greater ZWFL." (PMID 37571278, 2023). "Several lncRNAs are involved in different stages of insulin production and are linked to the development of insulin resistance." (PMID 37223012, 2023). "Given that continued hyperinsulinemia is associated with insulin resistance, a decrease in blood insulin levels by baicalin indicates improved action of this hormone on target cells." (PMID 38203600, 2023). "In visceral adipose tissue from obese individuals, insulin resistance is associated with decreased insulin/mTORC2 signaling and increased MCP1 generation." (PMID 37599681, 2023). "Chronic exposure to opioid drugs, such as morphine, is known to inhibit the insulin signaling pathway, leading to alterations in glucose homeostasis, and an increased risk of developing insulin resistance and associated comorbidities." (PMID 37507366, 2023). "Under the action of insulin, nitric oxide (NO) is required for glucose uptake and utilization, and uric acid affects the mechanisms associated with insulin resistance by blocking the biological effects of NO and interfering with endothelial function." (PMID 37138241, 2023). "During obesity, insulin resistance and the associated increase in insulin secretory demand lead to the overproduction of IAPP which, when in excess, is deposited and tends to form aggregates." (PMID 36671568, 2023). "The increase in insulin concentration caused by insulin resistance can enhance the reabsorption of sodium in renal tubules, thereby reducing the clearance rate of uric acid and causing the development of hyperuricemia." (PMID 36906544, 2023). "In both experimental and epidemiological studies, vitamin D deficiencies have been linked to decreased insulin release, insulin resistance, and T2DM." (PMID 37242192, 2023). "Impaired insulin production and secretion and/or a reduced response to insulin, also known as insulin resistance, are key underlying mechanisms leading to the development of type II diabetes." (PMID 37504117, 2023). "In these studies, serum HMGB1 levels directly correlated with plasma insulin levels, suggesting an association with insulin resistance." (PMID 37256493, 2023). "Accumulation of ECM components is increasingly recognized as an important pathogenic process that contributes to insulin resistance and metabolic dysregulation in insulin-sensitive tissues." (PMID 37383542, 2023).
Insulin resistance (continued). "Therein, the PI3K/AKT/GLUTS/GSK-3β pathway is a major pathway of insulin signaling transduction and an important pathway of blood glucose regulation, which is closely associated with insulin resistance-related diseases." (PMID 37091861, 2023). "The leading causes are insulin resistance and an insulin deficit brought on by the destruction of beta cells." (PMID 37954695, 2023). "The ROS overproduction disrupted mTOR/Akt signaling in the insulin‐sensitive target organs, causing insulin resistance." (PMID 37329278, 2023). "Serum resistin—and chemerin concentrations were positively associated with insulin resistance-markers, including insulin, FBG and HOMA-IR (p < 0.0001)." (PMID 36830883, 2023). "On the contrary, PPAR-α deficiency in a mouse model of obesity-related insulin resistance leads to reduced insulin secretion by pancreatic β-cells in response to glucose." (PMID 37513660, 2023). "Insulin resistance, a hallmark of T2D, is closely associated with inflammation in insulin-target tissues such as the liver, adipose tissue, and skeletal muscle." (PMID 37735474, 2023). "A high-fat diet causes central insulin resistance, and impairs the ability of insulin to lower hepatic glucose production, which is mediated via activation of hypothalamic p70 S6 kinase." (PMID 37153803, 2023). "In this review, we will address the pathophysiology of AD, evidence that AD is associated with insulin resistance, the process by which insulin resistance develops and its consequences in the brain, and the processes that lead to dementia." (PMID 36834911, 2023). "The beneficial effects of USP10 on insulin sensitivity were abolished by Sirt6 deficiency, and overexpression of Sirt6 strongly abrogated the insulin resistance observed in Usp10KO mice." (PMID 36834633, 2023). "As the interstitial fluid pH decreases, the insulin affinity to its receptor is diminished, causing insulin resistance." (PMID 37238649, 2023). "Hyperinsulinemia is primarily caused by increased insulin synthesis and release from pancreatic β-cells, either as a prior or compensatory response to insulin resistance." (PMID 37134142, 2023). "The inability of β-cells to properly compensate for decreased insulin sensitivity is a necessary condition for obesity and insulin resistance to be linked to type 2 diabetes." (PMID 37107924, 2023). "Prior to type 2 diabetes, susceptible individuals, while exhibiting insulin resistance, are nonetheless capable of maintaining normal blood glucose levels by increasing insulin secretion." (PMID 38004234, 2023). "MondoA regulates the expression of genes involved in glucose metabolism, glycogen synthesis, triglyceride synthesis, and insulin signaling, and it has been implicated in the development of metabolic diseases such as obesity, insulin resistance, and T2DM." (PMID 37240157, 2023). "Studies have shown that vitamin D deficiency is associated with an increased incidence of type 2 diabetes, and vitamin D supplementation can significantly increase insulin sensitivity in people with insulin resistance and vitamin D deficiency." (PMID 36713951, 2023). "Other studies have described greater associations between 1 hG and loss of first phase insulin than 2 hG, although both are associated with reduced insulin secretion and insulin resistance." (PMID 40303238, 2023). "GDM can also occur because of hyperglycemia, which has an antagonistic effect on insulin and leads to insulin resistance." (PMID 37107681, 2023). "Both diseases are strongly associated with elevated adipose tissue insulin resistance and high fasting levels of circulating insulin and FFA." (PMID 38260129, 2023). "Defective insulin-induced AKT phosphorylation is associated with obesity-related muscle insulin resistance." (PMID 36979708, 2023). "In the American adult population, acrylamide exposure was associated with the insulin resistance and a decrease in insulin levels." (PMID 37217800, 2023).
Insulin resistance (continued). "At the same time, as the main tissue of insulin-mediated glucose metabolism, the skeletal muscle has a significant inhibitory effect on insulin resistance, and the loss of muscle mass and strength is often the onset of insulin resistance." (PMID 37900136, 2023). "The degradation of INSR induced by high levels of insulin stimulation has also been demonstrated to cause insulin resistance in podocytes." (PMID 37884540, 2023). "Type 2 diabetes is caused by permanent hyperinsulinemia due to decreased insulin secretion, insulin resistance, or both." (PMID 37370930, 2023). "Recent research indicates that excessive production of aldosterone and associated activation of mineralocorticoid receptors (MR) impair insulin metabolic signaling, promote insulin resistance, and increase the risk of developing metabolic syndrome and CVD." (PMID 37610001, 2023). "Insulin resistance, a pivotal hallmark of type 2 diabetes, means that the action of insulin is insufficient." (PMID 38203600, 2023). "Obesity causes damages that can trigger an escalation in insulin resistance, prompting an elevated requirement for insulin to maintain optimal glucose levels." (PMID 38068717, 2023). "Oxidative stress is shown to cause insulin resistance by impairing insulin signal transduction and dysregulating adipokines." (PMID 37876013, 2023). "Insulin resistance is generally defined as reduced sensitivity of target tissues to insulin action or altered biological response of target tissues to insulin stimulation, resulting in reduced or loss of insulin-stimulated glucose uptake and utilization." (PMID 37867511, 2023). "EVs can be taken up by hepatocytes, muscle cells and other insulin target cell types and can cause an alteration in insulin signalling activation leading to disrupted normal metabolic responses of recipient sites to insulin causing insulin resistance." (PMID 36839984, 2023). "Increased insulin resistance and hyperinsulinemia both contribute to the increased risk of atherosclerosis, which would result in insulin‐related cardiovascular diseases." (PMID 37528628, 2023). "The mechanism by which tissue inflammation influences insulin sensitivity is unclear, but these molecules have been proven to interfere with the insulin receptor causing insulin resistance." (PMID 36826628, 2023). "Peripheral fat expansion is positively associated with insulin sensitivity, whereas ectopic fat accumulation is associated with insulin resistance." (PMID 36905117, 2023). "Identifying the association between gut microbiota and insulin resistance can help develop strategies to promote insulin sensitivity and manage obesity." (PMID 37189387, 2023). "Higher circulating IGFBP1 levels were strongly associated with greater insulin sensitivity (lesser insulin resistance) at ~ 26 weeks' gestation in the same cohort and two additional pregnancy cohorts." (PMID 37961187, 2023). "With an early diagnosis, insulin production-related genes were more influential in males (76.0% of R2) while peripheral insulin resistance-associated genes were more influential in females (52.3% of R2)." (PMID 37291636, 2023). "Type 2 diabetes mellitus (T2DM) is a metabolic disease characterized by hyperglycemia, which is caused by insulin secretion deficiency or/and insulin resistance (IR) caused by a combination of genetic and environmental factors." (PMID 37305429, 2023). "It results from insulin resistance causing a burden on pancreatic beta cells, which gradually lose their ability to produce insulin." (PMID 37947589, 2023). "Zn deficiency has been reported to decrease insulin sensitivity and cause insulin resistance (IR), whereas Zn supplements can decrease IR." (PMID 37711903, 2023). "T2DM is caused by systemic insulin resistance and impaired insulin secretion in pancreatic β-cells, leading to disorders of carbohydrate, protein, and lipid metabolism." (PMID 37960324, 2023).
Insulin resistance (continued). "Of the 166 GDM women followed up postpartum, rs62069863 in TRPV3 gene was positively associated with fasting insulin, homoeostasis model assessment of insulin resistance." (PMID 38087213, 2023). "The etiologic association between insulin resistance and acromegaly is mirrored by the correlations between insulin sensitivity markers and IGF-1 level; however, similar correlations with GH level are either not demonstrated or weaker." (PMID 36882643, 2023). "T2DM has a high prevalence around the globe and is characterized by several associated risk factors notably insulin resistance, glucolipotoxicity, and impaired insulin secretion, which leads to the malfunctioning of different body organs." (PMID 36837818, 2023). "It is characterized by insulin secretion deficiencies and systemic insulin resistance (IR) in adipose tissue, skeletal muscle, and the liver." (PMID 36333974, 2023). "These inflammatory markers will in return interfere with insulin signaling and cause insulin resistance." (PMID 36611151, 2023). "Increased plasma PAI-1 is associated with insulin resistance in people, and has been shown to cause insulin resistance in rodent models, and the plasma leptin/adiponectin concentration ratio correlates with insulin resistant glucose metabolism in people." (PMID 37159276, 2023). "Target genes of miRNAs associated with insulin signaling pathway and insulin resistance of common carp." (PMID 37091861, 2023). "Vegetarian diets are also associated with lower insulin resistance and lower fasting insulin levels, even in comparison with matched lean controls, and appear to improve healthspan and possibly also lifespan." (PMID 37854186, 2023). "In T2DM and obesity changes in the expression of adiponectin or adiponectin receptors decreases insulin sensitivity which leads to insulin resistance which in turn cause aggravation of the hyperinsulinemia." (PMID 37692464, 2023). "The presence of Roseburia has been associated with good cognitive abilities and increased insulin sensitivity, while insulin resistance is associated with high systemic branched-chain amino acid concentrations." (PMID 38068763, 2023). "In vulnerable individuals, insulin resistance induces a progressive loss of insulin secretion with islet pathology revealing a partial deficit of beta cells and islet amyloid derived from islet amyloid polypeptide (IAPP)." (PMID 36814640, 2023). "This chronic inflammation of adipose tissue is associated with increased insulin resistance, and impeding macrophage-specific pro-inflammatory signaling pathways improved insulin sensitivity in HFD-fed hosts." (PMID 37681868, 2023). "This inflammatory state set by COVID-19 can cause insulin resistance, which, in turn, increases oxidative stress in β-cells of pancreatic islets and peripheral tissues, resulting in impairment of insulin secretion." (PMID 37102024, 2023). "Other research suggests an association between maternal vitamin D deficiency and increased maternal insulin resistance, exposing the fetus to elevated glucose levels and thereby an increased fetal insulin production and risk of later metabolic disturbances." (PMID 37565036, 2023). "Underlying insulin resistance in type 2 diabetes has been attributed to defects in one or more components of the insulin signaling cascade." (PMID 37104182, 2023). "Over time, the increased insulin secretion in a person with high insulin resistance causes β-cell exhaustion, leading to T2DM." (PMID 37298483, 2023). "In the Attica study, it was found that adherence to the Mediterranean diet was linked to improved fasting glucose homeostasis, insulin levels, and a better insulin resistance index (HOMA) in both normoglycemic individuals and diabetic participants." (PMID 36901984, 2023). "High serum triglyceride levels and free fatty acids result in the deposition of lipid granules in various organs, that is known to inhibit insulin-associated signaling cascades resulting in insulin resistance." (PMID 37434784, 2023).